DYDC2 (DPY30 domain containing 2)
Synonyms: bA36D19.6; MGC16186
Tractability: Small molecule: a structure with a bound ligand is known.
Gene: Protein-coding gene on chromosome 10 (80,344,730 to 80,368,074, forward strand). Ensembl gene ENSG00000133665.
Subcellular location (Human Protein Atlas): Principal piece; Vesicles; Cytosol
Gene Ontology:
Molecular function: protein binding
Cellular component: axoneme; Set1C/COMPASS complex
Genetic constraint (gnomAD): Loss-of-function variants: 19 observed, 19.85 expected, observed/expected ratio (o/e) 0.96, 90% interval 0.67 to 1.4. The upper end of that interval is the gene's LOEUF score, 1.4, which puts it in group 5 of 6, group 1 being the genes least tolerant of losing a copy. Missense variants: 179 observed, 216.81 expected, observed/expected ratio (o/e) 0.83, 90% interval 0.73 to 0.94. Synonymous variants: 63 observed, 71.4 expected, observed/expected ratio (o/e) 0.88, 90% interval 0.72 to 1.09.
Homologues: Orthologues: chimpanzee DYDC2 (97% identical), macaque DYDC2 (94% identical), pig DYDC2 (73% identical), rabbit DYDC2 (55% identical), dog DYDC2 (52% identical), guinea pig DYDC2 (51% identical), mouse Dydc2 (46% identical), rat Dydc2 (42% identical), zebrafish dydc2 (25% identical), tropical clawed frog dydc1 (24% identical). Paralogues in human: DYDC1 (29% identical).
Diseases named in the same sentence as DYDC2 in open-access papers:
DYDC2 is named in the same sentence as 3 diseases in open-access papers, as found by Europe PMC text mining. Sharing a sentence is not in itself a finding about the gene and the disease. The quoted sentences say what the papers report.
colon cancer (1 paper, 2020). "By studying colon cancer pathologic specimens, we confirmed that DYDC2, MS4A15, MAGEA1, WNT7A, APOD, and SERPINE1 were highly expressed in colon cancer tissues." (PMID 33680915, 2020).
DYDC2 also shares sentences with these, for which no sentence is quoted: autism (1 paper); breast carcinoma (1).